EGFR (epidermal growth factor receptor)
Diseases named in the same sentence as EGFR in open-access papers (continued):
Sharing a sentence is not in itself a finding about the gene and the disease.
tumor (continued). "Compared to normal brain tissue, viable tumor tissue overexpressed EGFR, corresponding to a higher mean fluorescence intensity (2.0 vs 0.6, P < 0.0001)." (PMID 34158840, 2021). "The epidermal growth factor receptor (EGFR) contributes to tumor malignancy via gene amplification and protein overexpression." (PMID 34944112, 2021). "Toripalimab plus chemotherapy showed a promising anti-tumor activity with acceptable safety profiles as the second-line setting in patients with EGFR-mutant NSCLC." (PMID 34650034, 2021). "Confocal microscopy and in vivo imaging analyses of TNBC xenografts demonstrated the targeting ability of CL4-equipped nanoparticles to EGFR-positive tumor cells." (PMID 34294133, 2021). "The combination reversed MDSC-induced immunosuppression and improved antitumor immunity with increased circulating tumor antigen-specific T cells (EGFR specific) and increased the number and function of tumor-infiltrating CD8 T cells." (PMID 33718169, 2021). "The patient was treated with gefitinib (EGFR inhibitor, first generation) which induced tumor response once more." (PMID 33969622, 2021). "LipoMag/siRNAEGFR#4-mU (siRNA to efficiently knock down the EGFR mRNA in tumor vessels) treatment under a magnetic field exhibited a ≈50% reduction in the tumor volume compared with the control group on day 28th after the treatment initiation." (PMID 34834342, 2021). "The TGFβ-TGFβR and EGFR-NRG1 binding between receptor and ligand was obvious in CAF/CT26 subgroups, revealing that the CAFs and CT26 tumor cells cross talk through TGF pathway and affect the expression of EGFR to transform the tumor cells." (PMID 34026600, 2021). "The small leucine-rich proteoglycan decorin (DCN) is an important component of the cellular microenvironment and has been shown to inhibit the growth of a wide variety of tumor cells, probably due to an interaction of the decorin core protein with EGFR." (PMID 34283070, 2021). "Other than the striking in-vitro antiproliferative profile, the hybrid scaffold was also endowed with tumour growth inhibitory potential as evidenced in human EGFR-resistance NSCLC H1975 xenograft model in vivo." (PMID 33840388, 2021). "This ligand independent dimerization is extremely relevant in tumor cells where overexpression of the EGFR molecule can lead to increased activation, thereby promoting pathways for tumorigenesis." (PMID 34298761, 2021). "Specifically, EGFR is overexpressed in a large number of tumours of epithelial origin, such as in 15–30% of breast cancers, 60% of lung cancers and 25–77% of CRC." (PMID 34829955, 2021). "EGFR has been a favourable target for the treatment of mCRC since the last decade, mainly because they are highly expressed in most human tumours, including CRC." (PMID 34733591, 2021). "It ultimately leads to the activation of the kinase, which contributes to enhanced EGFR signalling and promotes tumor development." (PMID 34578147, 2021). "In GB, ~20% of classical tumours express a truncated form of EGFR that lacks exons 2–7 (EGFRvIII) and is constitutively active." (PMID 33432111, 2021). "These patients were authorised to receive EGFR inhibitors as first-line treatment for tumour recurrence, in agreement with the guidelines." (PMID 34064047, 2021). "In the present study, phenformin strongly inhibited cell proliferation and tumor growth in NSCLC with acquired EGFR-TKI resistance." (PMID 34367462, 2021). "EGFR enhances cell proliferation, migration, invasion, and survival and thus contributes to tumor progression." (PMID 33440835, 2021). "For example, miR-634 synergizes with EGFR inhibition to reduce tumor growth in mice while restoring miR-3619–5p expression in cisplatin resistant cell lines improves chemotherapy efficacy." (PMID 34553848, 2021).
tumor (continued). "One high-throughput immuno-oncology screen identified the EGFR inhibitor erlotinib as a potent enhancer of antigen-specific CTL tumor cell killing, synergizing with anti-PD-1 checkpoint inhibition to suppress colon cancer growth." (PMID 33807608, 2021). "Such basal EGFR signaling sustains slow tumor proliferation and survival, contributing to the escape of the cancer cells under TKI therapy." (PMID 34211836, 2021). "The effect of EphA2 on tumor resistance is also mediated by its physical and functional interaction with ErbB2/EGFR and the subsequent activation of signaling pathways that involve Ras/MAPK and RhoA." (PMID 33572284, 2021). "EGFR mutations were identified in 4/40 (10%) HER2-negative tumours and 2/29 (6.9%) HER2-positive tumours." (PMID 33933113, 2021). "HER2 belongs to the epidermal growth factor receptor (EGFR) family of tyrosine kinase receptors, which play a pivotal role in carcinogenesis as well as in propagation of tumor cell growth and survival." (PMID 34680363, 2021). "A milestone was achieved by Simpson groups, who recently revealed that tumours can be classified based on EGF endocytosis profile from an ex vivo EGF endocytosis assay to predict antibody-based anti-EGFR therapy efficacy." (PMID 34831480, 2021). "Currently, about 20 combination clinical trials with an anti-PD1/L1 are ongoing in localized and advanced stages, in association with radiotherapy, chemotherapy, tumor vaccines, anti-CTLA4, anti-EGFR, or antiangiogenic molecules." (PMID 34359795, 2021). "In LGG patients, we also observed high expression of EGFR in tumor tissues compared to the corresponding normal brain tissues." (PMID 34552618, 2021). "Nimotuzumab is a new humanized anti-EGFR MAb that binds to the extracellular domain of the EGFR with intermediate affinity and high specificity which results in the blockade of receptor-dependent signal transduction pathways and provides anti-tumor effects." (PMID 34104833, 2021). "This bispecific VHH was shown to trigger activation of CD16+ NK cells, resulting in enhanced cytotoxicity of EGFR+ tumor cell lines and EGFR+ patient CRC specimens in both an autologous and allogeneic setting." (PMID 34771609, 2021). "Unfortunately, acquisition of the EGFR T790M missense mutation, occurring in 50% of NSCLC, was found to cause structural changes in the EGFR binding pocket, thus rendering tumor cells resistant to the second generation of TKIs and requiring new treatments." (PMID 33809714, 2021). "In LOVO xenograft tumor models with positive EGFR expression, the combination of cetuximab and NK cells showed great antitumor effect." (PMID 34178645, 2021). "show that loss of PTEN conferred independence from EGFR activity and resistance to EGFR inhibition by CTX in terms of downstream signaling, proliferation, and tumor growth both in vitro and in in vivo xenograft models." (PMID 33718169, 2021). "We compared the results of EGFR analysis using tissue DNA (tDNA) and circulating tumor (ctDNA) to evaluate the feasibility of plasma as an effective material for detecting EGFR mutation and the reliability of ctDNA analysis in real-world practice settings." (PMID 34574036, 2021). "Since antibody-dependent cellular cytotoxicity (ADCC) is known to contribute to the anti-tumor activity of cetuximab, we constructed an anti-EGFR fusion protein using an IgG1 backbone." (PMID 34831127, 2021). "First- or second-generation EGFR tyrosine kinase inhibitor (EGFR-TKI) therapies in previous trials have been shown to induce robust tumor regression that lasts for 9–12 months on average." (PMID 34205733, 2021).
tumor (continued). "The SEER-Medicare linked database lacks information on the status of tumor mutations, including KRAS and NRAS (biomarkers of exclusion from anti-EGFR therapy), and BRAF (biomarker of poor prognosis)." (PMID 34910154, 2021). "The bispecific VHHs only induced statistically significant degranulation of NK cells and lysis of tumor cells when tumor cells expressed EGFR and NK92 cells expressed CD16." (PMID 34771609, 2021). "Despite most of the patients responding well to the EGFR target therapy, tumor recurrence eventually occurs within 9–14 months in these patients, due to the development of drug resistance." (PMID 33562150, 2021). "Our work also validated that cinobufagin inhibited tumor growth and elongated nude mice life span via blocking EGFR and STAT3 signaling pathways and inducing apoptosis in vivo." (PMID 34925034, 2021). "Conjugation of IR700 to epidermal growth factor receptors (EGFR)—targeting panitumumab (Pan-IR700) showed selective uptake in EGFR expressing A431 cells and effective tumor shrinkage after irradiation was observed in EGFR expressing A431 tumors." (PMID 34203805, 2021). "Unlike erlotinib treatment or dox withdrawal, which result in reduced phosphorylated EGFR (pEGFR) levels in tumor-bearing lungs, DT-treated tumors maintained pEGFR levels comparable to those of vehicle- and CRM197-treated tumors." (PMID 34494649, 2021). "In CRC, methylation of R198/200 in the extracellular domain of EGFR by PRMT1 enhanced receptor dimerization and cell proliferation, resulting in tumor cell resistance to the anti-EGFR monoclonal antibody cetuximab." (PMID 33420374, 2021). "Through the use of scRNA-seq, EGFR-mutant tumor cells were found to be significantly different from other NSCLC tumors." (PMID 33712615, 2021). "This BRAF mutation also counters any therapeutic effect from the EgA1 anti-EGFR component in the LiTE that also blocks EGFR signalling and tumour growth." (PMID 33686177, 2021). "In many types of cancers, intracellular pathways modulated by EGFR have been identified as crucial factors influencing tumor survival and development." (PMID 33435596, 2021). "When assessing the treatment response in the RAS and BRAF wildtype cohort there was a clear difference in response to anti-EGFR for the CMS4 tumours between both trials." (PMID 34253874, 2021). "The epidermal growth factor receptor (EGFR) is overexpressed on 38–47% of HNSCC tumours and is a poor prognostic marker." (PMID 34383182, 2021). "The ideal combination of immunotherapy with EGFR-TKIs should target different mechanisms of tumour-induced immunosuppression in the microenvironment." (PMID 34332557, 2021). "Arm E is enrolling patients with EGFR-mutated NSCLC after progression to osimertinib, including only patients whit c-Met overexpression assessed on tumor tissue obtained post-osimertinib progression." (PMID 33509252, 2021). "Recent advances in tumor molecular biology have resulted in the identification of several candidate biomarkers, such as EGFR, that can be used in the diagnosis of MPLC." (PMID 34109114, 2021). "Osimertinib-resistance mutations or amplifications in EGFR/MET were identified by NGS in both liquid and tumour biopsies." (PMID 34898564, 2021). "Age at initial pathologic diagnosis of patients with wild-type EGFR was positively correlated with tumour grade." (PMID 34205437, 2021). "STAMBP expression is elevated in the cytoplasm of tumor cells, which provides further support for its roles in regulating EGFR stability and promoting EGFR recycling to the membrane." (PMID 34102455, 2021).
tumor (continued). "Examples are COL4A6, WNK2 and STK32B whose roles have been assigned in processes such as prevention of early invasion stages, negative regulation of epidermal growth factor receptor signaling and opposite correlation with tumor size, respectively." (PMID 33691672, 2021). "The first limitation of this study is that the patients in our study had a tumor response evaluation per 8–12 weeks after EGFR-TKIs were taken." (PMID 34692766, 2021). "Subgroup analysis of clinical trials showed that the efficacy of tumor immunotherapy was better in the KRAS group than in the EGFR group." (PMID 34136375, 2021). "Tumor-cell-derived exosomes containing EGFR were found to induce the angiogenic response of endothelial cells." (PMID 34680445, 2021). "Treatment of the tumor cells with TGFα-PE38 increased the expression of EGFR in the cells and induced tumor cell apoptosis." (PMID 33738260, 2021). "The sensitivity of low-affinity ADC RN765C was evaluated in a panel of EGFR-expressing tumor cells, resulting to be higher in FaDu cells (Ec = 0.806 nM) compared to normal human epidermal keratinocytes." (PMID 34206707, 2021). "Objective response rate (ORR) and PFS were similar for patients with T90M detected in tumor or plasma, when treated with the third-generation EGFR-TKI Osimertinib." (PMID 33925308, 2021). "Like its predecessors, depatux-m and ABBV-221, ABBV-321 binds a cryptic EGFR epitope located on the cell surface, exposed primarily in tumors when the receptor is activated, thereby providing tumor selectivity." (PMID 34206707, 2021). "Tumor progression is driven by acquired resistance mechanisms (ARMs) to EGFR TKIs, which are quite heterogenous molecular alterations." (PMID 34575554, 2021). "The study identified an upregulation of Lnc-EGFR in Tregs and was well-correlated with the expression of EGFR/Foxp3 and tumor size, but negatively correlated with IFN-γ expression." (PMID 34303380, 2021). "CMTM7 is a tumor suppressor that positively regulates EGFR degradation by promoting Rab5 activation, and plays a vital role in tumor progression." (PMID 34281589, 2021). "This study reported that blockage of EGFR with cetuximab in AsPC-1 xenograft tumors decreased the tumor uptake of the radiotracer up to three folds while blocking the HER3 receptors with DL3.6b did not alter the radiotracer uptake." (PMID 34400948, 2021). "Paracrine loops comprising tumor and stromal cells enable EGFR to fuel invasion across tissue barriers, survival of clusters of circulating tumor cells, as well as colonization of distant organs." (PMID 34206026, 2021). "Taken together, these data suggest that EGFR TKIs induce a tumor cell-intrinsic IFN response that communicates with the TME to increase T-cell infiltration that contributes to therapeutic response." (PMID 34001994, 2021). "NK cell-mediated ADCC against MICA/B bearing differentiated tumor cells in the presence of MICA/B antibody was compared to that mediated by the antibodies against EGFR and PDL1." (PMID 33440654, 2021). "If one were to assess the tumor resistance mechanisms in NSCLC patients receiving treatment with EGFR‐TKIs, a repeat biopsy (re‐biopsy) would be necessary." (PMID 33131198, 2021). "In mixed-breed dogs’ high tumor proliferation index was associated with the overexpression of RAC1, EGFR and VEGF-B, and moderate and strong correlations were found between PI and FLT1, EGFR and VEGF-B." (PMID 34679042, 2021). "Combination treatment with anti-VEGF and anti-EGFR antibodies demonstrated synergistic activity in vitro, and tumour growth and angiogenesis were strongly suppressed in an in vivo xenograft mouse model." (PMID 34663410, 2021). "GBM still remains a challenge because these tumors are resistant to anti-EGFR therapy, always relapse and recurrent tumors are less sensitive to chemotherapy than the primary tumor, developing novel anti-EGFR agents remains urgent." (PMID 34925034, 2021).
tumor (continued). "In this study, we found that cetuximab exerted anti-tumor effect in EGFR-overexpressed MDA-MB-468 cells via the inhibition of EGFR." (PMID 33472170, 2021). "Tumor-derived exosomes also promote tumor progression through other mechanisms, such as via inflammation-related pathways, induction of the EGFR pathway in preosteoclasts, or interactions with adjacent cells." (PMID 34511114, 2021). "In patients with EGFR Del19- or L858R-positive tumours, median PFS was 18.2 months and 12.9 months, respectively." (PMID 33648453, 2021). "In conclusion, the results demonstrated that FGFC1 inhibited NSCLC tumor growth via regulating EGFR signaling pathways." (PMID 35126111, 2021). "We interestingly found that EGFR inhibitor suppressed EGFR expression and corresponding tumor cell growth, but its inhibition on cell proliferation was even lower than the control level, regardless of decreased EGFR expression comparable to control levels." (PMID 33414368, 2021). "Analysis of circulating tumor DNA from NSCLC patients revealed that 46% of patients treated with EGFR inhibitors have multiple drug resistance mechanisms." (PMID 34203709, 2021). "Together, this highlights the role of additional genetic and molecular modifications in mediating both EGFR mutant tumor progression and in allowing cells to bypass or reactivate EGFR signaling in the context of targeted therapy." (PMID 34944063, 2021). "Based on our results, the consumption of the fruits appeared to influence EGFR, which was reported to be involved in a diversity of tumours." (PMID 34579001, 2021). "Acquired drug resistance refers to the process by which tumor cells sensitive to previous treatments evade the influence of new drugs by changing their own metabolic pathways after contact with the third EGFR-TKI." (PMID 34575576, 2021). "Previous study has indicated that the inactivation of MSMO1 markedly sensitized tumor cells to therapeutic anti-EGFR antibody via increased EGF receptor degradation." (PMID 34893642, 2021). "Nuclear-EGFR acts as a transcription factor regulating gene expression and cellular processes involved in tumor biology." (PMID 34445451, 2021). "Blocking YAP signaling pathway contributes to eliminate tumor cells upon EGFR-TKI or MEK inhibitor treatment." (PMID 34102455, 2021). "It has been reported that a minority of patients with wild-type EGFR respond to EGFR-TKI therapy in terms of tumor recurrence." (PMID 34680445, 2021). "EPOC trial data recommended complete avoidance of a combination of an anti-EGFR agent plus oxaliplatin, even in patients with left-sided tumours." (PMID 34440099, 2021). "The only mutation in the EGFR ECD was Y112C, which was detected in the PD1 sample of a patient with an RAS wild type tumor, who received first-line anti-EGFR therapy." (PMID 34943612, 2021). "Our data emphasize the need for analyses of SR tumor tissues at a multi-omics level for a more differentiated molecular understanding of anti-EGFR SR in CRC." (PMID 34271981, 2021). "In this study, we demonstrate that KTN1 knockdown induces EGFR degradation in cSCC cells by promoting the ubiquitin-proteasome system, and that this effect is tumor cell-specific." (PMID 34689164, 2021). "ARIH2 knockout results in an increased fraction of cells that enter a DTP state following treatment with an EGFR inhibitor and results in increased tumor size in vivo." (PMID 34944063, 2021). "We found that c-MET and EGFR expression levels were independent biomarkers for clinical prognosis, and their high expressions were correlated with tumor progression and a poor prognosis of CRC." (PMID 34512327, 2021). "Univariate analysis revealed that sex, smoking status, tumor volume, spiculation, air bronchogram, necrosis, CEA, SCC, CYFRA21-1 and NSE were significantly associated with EGFR-activating mutations." (PMID 34422624, 2021).